CXCR4 (C-X-C motif chemokine receptor 4)
Diseases named in the same sentence as CXCR4 in open-access papers (continued):
Sharing a sentence is not in itself a finding about the gene and the disease.
tumor (continued). "The only receptor to be consistently expressed in all, but especially in A-498 tumour cells was CXCR4 (data not shown)." (PMID 11953881, 2002). "While none of the analysed tumour cell lines expressed CXCL12α, A-498 cells were found to express CXCR4." (PMID 11953881, 2002). "However, the administration of mifepristone, a glucocorticoid receptor inhibitor, did not suppress CXCR4 expression in tumor‐infiltrated CD8+ T cells, suggesting that glucocorticoid signaling has a minimal effect on CXCR4 regulation in these cells." (PMID 41257391, 2026). "Moreover, DPP-4i could have anti-cancer effects by modulating the DPP-4/SDF-1/CXCR4 axis and the immune balance, enhancing tumor rejection by preserving biologically active CXCL10 and increasing trafficking into the tumor by lymphocytes." (PMID 40175622, 2025). "The CXCL12/CXCR4 axis may help maintain this dormant state through activation of downstream signalling pathways (e.g., PI3K/AKT, ERK1/2) and interactions with the tumour microenvironment, including stromal and immune cells, which support cell survival without promoting proliferation." (PMID 41002447, 2025). "Cancer stem cells (CSCs) drive tumor initiation, progression, and chemoresistance through dysregulated molecular pathways that include Wnt/β-catenin, Notch, and Hedgehog signaling, with key markers such as CD133 and CXCR4 contributing to stemness maintenance and metastasis." (PMID 41035670, 2025). "In the tumor microenvironment, PKM2 promotes tumor cells to release cytokines and aggregates a large number of MDSCs around tumor cells, PKM2 facilitates the binding of cytokines, such as CXCL1 and MIF, released by tumor cells to the surface receptors CXCR2 or CXCR4 on MDSCs." (PMID 40948745, 2025). "Additionally, APS may interfere with the CXCR4/CXCL12 (SDF-1) chemokine axis, reducing Treg infiltration into tumour sites and consequently enhancing antitumour immune responses." (PMID 40649307, 2025). "The role of CXCR4 in metastatic spread has been extensively studied, with findings demonstrating its involvement in vascular endothelial growth factor (VEGF)-mediated angiogenesis, tumor cell invasiveness, and the formation of metastatic niches in bone marrow and liver." (PMID 41024311, 2025). "Ulocuplumab (BMS-936564), a human monoclonal antibody against CXCR4, and MSX-122, a small molecule inhibitor with partial agonist properties that modulates tumour cell migration without altering normal haematopoiesis, are other investigational CXCR4 antagonists." (PMID 41002447, 2025). "Furthermore, CTHRC1 has been shown to enhance GC metastasis via the HIF-1α/CXCR4 signaling pathway; it upregulates CXCR4 expression through HIF-1α and facilitates the migration and invasion of cancer cells, promoting tumor spread to distant organs, thus playing a crucial role in metastasis." (PMID 40978044, 2025). "The use of CXCR4 antagonists, such as plerixafor (AMD3100), balixafortide, and POL5551, is one such approach that, in tandem with standard chemotherapeutics (e.g., doxorubicin or paclitaxel), produced a synergistic effect, resensitizing TNBC cells to apoptosis, and reduced tumour burden." (PMID 41002447, 2025). "Furthermore, the infiltration of F4/80+ macrophages, M2 and CXCR4+ macrophages in peritumor intestine, which was stimulated by HIF2A-overexpressed exosome, was also significantly decreased, as was the attenuation of tumor cell infiltration." (PMID 40756343, 2025). "Also, tumor-derived MIF enhances the expansion and migration of Th17 cells through CXCR4 signaling." (PMID 41159021, 2025). "Furthermore, CXCR4 expression appeared stage-dependent: it was more pronounced in plaque-stage MF than in patch- or tumor-stage lesions, where expression was weak or absent." (PMID 40861461, 2025). "Additionally, CXCR4/CXCL12 signalling enhances CSC populations to mediate resistance by retaining a portion of quiescent, drug-tolerant cells, which are capable of repopulating the tumour after treatment is paused." (PMID 41002447, 2025).
tumor (continued). "In the GL261 murine GBM model, combination immunotherapy with anti-CXCR4 and anti-PD-1 significantly reduced CD11b+ macrophage and monocytic MDSC infiltration while lowering the proportion of CD4+FoxP3+ Treg cells, thereby enhancing CD8+ tumor-infiltrating lymphocyte (TIL) cytotoxicity." (PMID 41002423, 2025). "Additionally, it has been demonstrated that Hg (methylmercury) might influence the tumor microenvironment by modulating the secretion of CXCL12, the ligand for CXCR4, in the cerebrum of the 129/Sv mice." (PMID 40362664, 2025). "Given the importance of CXCR4 in GBM recurrent tumours and GSCs, and the clinical benefits seen with 177Lu-based TRT in other solid cancers, our study highlights the need to develop effective CXCR4-TRT that can eliminate CXCR4 + GBM tumour cells with minimal damage to non-target tissue." (PMID 39008219, 2024). "The high CXCR4 expression in the TNBC primary xenograft tumors, but not in the cell culture, caused us to ask if the CXCR4 stromal-expressed ligand, CXCL12, was responsible for the MDMX-associated upregulation of CXCR4 in the tumor." (PMID 39766093, 2024). "Thus, it is not surprising that CXCR4 showed significant differences in neoplasm histologic grade, OS, pathologic T, and tumor stage." (PMID 38221932, 2024). "Administering AMD3100, a CXCL12 receptor, chemokine receptor 4 (CXCR4, SE = 13.1) inhibitor, inhibited CXCR4 in tumor cells and moreover induced rapid T-cell accumulation, which acted synergistically with the PD-L1 antibody to greatly diminish PDAC tumor cells." (PMID 38892190, 2024). "However, no study has elucidated the specific molecular mechanisms by which the CXCL12/CXCR4/ACKR3 axis activates the JAK2/STAT3 pathway, and responses to the CXCL12/STAT3 signal transduction may vary across different tumor types and cell lines." (PMID 38920657, 2024). "Altogether, putatively tumor-reactive DP CD8+ T cells expressed higher levels of coinhibitory markers, had a higher proliferative capacity, and acquired a unique chemokine receptor expression profile by the upregulation of CCR5 and CXCR6 and downregulation of CXCR3 and CXCR4." (PMID 38335302, 2024). "Recent studies have shown that the CXCR4 antagonist AMD3100, also known as plerixafor (Marketed Mozobil® (Sanofi, Paris, France)), effectively blocks the CXCL12/CXCR4 interaction, thereby inhibiting the migration of Tregs and other immune cells within the tumor microenvironment." (PMID 39273290, 2024). "CXCL12 bound to its specific G protein-coupled receptor CXCR4 induces a plethora of downstream signaling events involving ERK1/2, RAS, PLC/MAPK, p38 MAPK, and SAPK/JNK, which are in turn responsible for various biological and pathological processes including angiogenesis and tumor metastasis." (PMID 38182756, 2024). "Finally, VM structures provide vascular channels for neutrophil infiltration and activation, leading to their expression of arginase, CCL2, CXCR4, and MMP-9 to promote angiogenesis and evade anti-angiogenic therapy, collectively suggest a critical role of neutrophils for tumor angiogenesis." (PMID 38580870, 2024). "The activation of the MIF - (CD74+CXCR4) axis indicates that IGF2BP1-overexpressing tumor cells may facilitate immune evasion through this pathway, consequently undermining anti-tumor immune responses and adversely impacting patient prognosis in immunotherapy contexts." (PMID 39512352, 2024). "For example, the blocking of CCL2 can inhibit metastasis of tumors and interrupt the CXCR4/CXCL12 chemokine axis, which can be used to sensitize drug-resistant tumor cells to chemotherapy or radiotherapy and may inhibit angiogenesis and proliferation of tumor cell." (PMID 38578317, 2024). "A significant difference in BM uptake between individuals with or without CXCR4-positive tumor burden could not be observed (p = 0.309)." (PMID 38082196, 2024).
tumor (continued). "Furthermore, an analysis utilizing the TSIDB database uncovered a significant correlation between AEG-1 and several key factors, including the tumor-promoting cell Th2, immune activator IL6, CXCR4, immunosuppressants CTLA4, IL1, IDO1, LAG3, PDCD1, TGFB1, and the DHC molecule HLA-DPA1." (PMID 39483471, 2024). "used a PLGMWSR‐OH linker to design CXCR4‐targeted iron oxide nanoparticles (IONPs) which could be activated by MMP‐9 and self‐assembled to give a T2 signal enhancement by about 160% in U87.CD4.CXCR4 tumor." (PMID 39175888, 2024). "For example, CXCR4-targeted lipid-coated PLGA NPs with sorafenib and AMD3100 (a CXCR4 antagonist) revealed that blocking the interaction of TAM CXCR4 with SDF1α reduced M2-like macrophage polarization and TAMs infiltration, and simultaneously tumor progression was delayed in a mouse model of HCC." (PMID 37483594, 2023). "However, the potential of CXCR4 as a tumor immune prognostic marker has not been extensively studied, especially in NSCLC." (PMID 36308553, 2023). "Although not analyzed, these antecedents suggest that CXCR4 could be preferentially accumulated in the nucleus of tumor cells in our cohort." (PMID 37444550, 2023). "Lastly, a Nb-Fc conjugate against the chemokine receptor CXCR4 was shown to exert antibody-dependent cellular cytotoxicity and to complement dependent cytotoxicity effector functions on CXCR4 overexpressing tumor cells, with no side reactions to cells expressing none or low levels of CXCR4." (PMID 36983063, 2023). "Chemokines secreted by TAMs, including CCL3, CCL5, CCL15, CCL18, CXCL8 and CXCL12, promote tumor metastasis, angiogenesis, cancer cell survival, immunosuppression and resistance of cancer cells after chemotherapy via CCR1/5, CCR5, CCR1, CCR8, CXCR1/CXCR2, CXCR4, respectively." (PMID 36173487, 2023). "Flow-cytometric analysis showed the presence of different pituitary lineages (which may originate from the tumor and/or adjacent tissue), as well as enrichment of the TBX19+ (corticotrope) lineage and stem cells (marked by SOX2, CXCR4 and CD133), similar to the patient’s tumor." (PMID 37614709, 2023). "Interestingly, tumor-secreted protein NAMPT acts as a rate-limiting enzyme in the upstream pathway of SIRT1, which restricts the OXPHOS of aged neutrophils (CD45+CD11b+Ly6G+CXCR4+CD62Llo) and prolongs the lifespan of neutrophils by mitophagy." (PMID 38023616, 2023). "Moreover, CXCR4 may influence multiple signaling pathways such as PI3K/AKT, ERK1/2, JNK and c-Jun to modulate tumor progression." (PMID 38129870, 2023). "Based on the difference in CXCR4 expression in the stroma in non-tumor tissues compared with tumor pancreatic tissues in these 23 patients, we analyzed the clinicopathological data and the association between underexpression and overexpression profiles of CXCR4." (PMID 37697316, 2023). "In addition, although intercellular communication between tumour cells and the CXCL12/CXCR4 signalling pathway has been widely studied in tumour chemotactic and metastatic processes in many cancer types, few studies have focused on the effect of NPM1 in CXCL12-mediated HCC chemotaxis and migration." (PMID 37251542, 2023). "Moreover, a high MRP2/CXCR4/PD-L1 co-expression is associated with increased survival time (30 vs. 6 months, p = 0.0025) in GBC patients, regardless of tumor stage." (PMID 37444550, 2023). "Therefore, we hypothesized that TA on the ICG-Glow NPs efficiently binds to EGFR, CXCR4, FASN, and other oncoproteins, thus facilitating tumor specific binding/targeting which can further provide a novel option for tumor specific probe development." (PMID 37151801, 2023). "By studying a model of spontaneous lung metastasis induced by the tumor cell line 4T1, investigators also discovered that CXCR4 was expressed on tumor-draining lymph node B cells, which could attract CXCL12-producing 4T1 cells and kill tumor cells by the perforin pathway." (PMID 37215990, 2023).
tumor (continued). "Another study has suggested that impaired primary tumor development and metastases in orthotopic esophageal carcinoma models upon direct inhibition of HER2 might be attributable to resultant suppression of CXCR4 expression." (PMID 35093187, 2022). "The activation of macrophage phagocytosis of tumor cells and co-presentation of their antigens may synergize with the chemoattractant activity of CXCL12 towards monocytes and macrophages, with CXCR4-TCR co-signaling in the immune synapse and with BCR co-signaling in mature B cells." (PMID 35565443, 2022). "CXCR4 blocking has been evaluated in several clinical trials as a strategy to reduce cancer development, but since this chemokine is abundantly expressed at both tumor and non-tumor sites, CXCR4 blockade specifically in tumors can be difficult." (PMID 35155581, 2022). "The advantage of 177Lu-Pentixather over PSMA might be that 177Lu-Pentixather can be directed at tumour cells and neovasculature when CXCR4 is present, unlike PSMA which only targets the neovasculature." (PMID 36140541, 2022). "Under hypoxia, activation of HIFs and their downstream signaling pathways (including CXCR4, M-CSFR, and CD47) regulate the tumor-specific immune response, with production of several immunosuppressive cytokines and growth factors to allow for immune escape and promoted tumor progression." (PMID 35659268, 2022). "Besides, cluster 2 and 3 overexpressed genes CXCR4 and CXCL8 for tumor microenvironment." (PMID 35986270, 2022). "In addition, the tumor tissue of the DEN/CCl4-treated WT mice shows a reduction of chemokine receptors levels compared to the surrounding tissue of the same mouse (Ccr5, Ccr2, Ccr7, Ccr1 and Cxcr4)." (PMID 35897689, 2022). "Finally, CXCR4 signaling, where TNC induces CXCL12 in tumor cells (through TLR4), but also binds to CXCL12 (again in the TN3–TN5 domains) thus trapping CD8T cells in the stroma, exerting a Janus function (i.e. both activation and inhibition) on yet another pathway." (PMID 36102918, 2022). "Therefore, CXCL12 promotes communication between cancer cells and the surrounding non-neoplastic cells in the tumor microenvironment, including endothelial cells and fibroblasts, through activation of CXCR4 and CXCR7." (PMID 35406582, 2022). "By combining the evaluation of the chemokine axis CXCR4/SDF-1 in relation to CD8+ density, the survival analysis in this study suggests that the detrimental effect of high CXCR4/SDF-1 expression depends on the density of tumor-infiltrating CD8+ cytotoxic T-lymphocytes." (PMID 36419107, 2022). "The CXCR12/CXCR4 axis has emerged as a potential therapeutic target through the activation of multiple signaling pathways, such as ERK1/2, Ras, p38 MAPK, PLC/MAPK, SAPK/JNK, and regulation tumor stem cells, which play a vital role in tumor initiation and progression." (PMID 35958625, 2022). "Moreover, although the BxPC3 cell line selected in our study has a moderate expression of CXCR4 and integrin αvβ3, BxPC3 tumors could still be visualized clearly by 68Ga-yG5-RGD because of its high tumor uptake." (PMID 36145541, 2022). "However, adding ICI to AAT and CXCR4 inhibition alleviated these resistance mechanisms further by increasing the amount of IFNγ and CD8+ T cells in the tumor center, indicating that vessels could be further normalized." (PMID 35712656, 2022). "In this regard, such a tumor sink effect may then also have a significant impact on both radiolabeled and non-radiolabeled CXCR4-targeted therapies." (PMID 35312939, 2022). "However, using the endothelial cell line HUVEC, it was shown that this expression by vessels is not necessary for CXCL12-mediated transendothelial migration, and this process requires CXCR7 expressed by tumor cells, without involving CXCR4." (PMID 35406582, 2022).
tumor (continued). "In addition, RT-induced TGF-β signaling increases the number of CAFs whose release of CXCL12 binds to the ligands CXCR4 and CXCR7, exerting pleiotropic pro-tumor activity, including induction of tumor survival, metastasis and affecting immune cell infiltration, and function." (PMID 36532071, 2022). "Chemokine analysis highlighted CCR2, CXCR2, CXCR4 and C5aR ligands/chemoattractants as possible targets to decrease the immune myeloid suppressive cells in NMIBC, but also revealed a complex chemokine crosstalk, which deserve particular attention to design novel anti-tumor-treatments." (PMID 36613562, 2022). "Clearly, both WB and IF showed that shRNA silencing CXCR4 synergistically enhanced the effect of PTX treatment on decreasing Akt phosphorylation and the resulting reduction in N-cadherin, vimentin, snail, CD44, CD133, and NANOG protein expression in OVCA420 tumor tissues." (PMID 35681259, 2022). "However, our study suggests that a high secretion of chemokines in general is associated with fewer T cells within the desmoplastic tumor since this observation was not confined to CXCR3 ligands, but also to the CXCR4 and CCR5 ligands." (PMID 35954489, 2022). "Here, we found that the expression of CXCR4 was downregulated and accompanied by a decrease of p-AKT after intervention with the extracted compound, similar to previous research that showed overexpression of PTEN dramatically attenuates tumor expansion in the lung via AKT/CXCR4 signaling." (PMID 36364935, 2022). "Furthermore, MIF promotes tumor proliferation, migration, invasion, angiogenesis and chemotherapy resistance via binding to different receptors, including CD74, C-X-C motif chemokine receptor 2 (CXCR2), CXCR4, and CXCR7." (PMID 35842634, 2022). "Our results demonstrate that the T22-PE24-H6 nanotoxin displays a potent CXCR4-dependent cytotoxic effect in CRC cells and also that its use at low doses in a repeated treatment regime is capable of inhibiting tumor growth and metastasis development without associated systemic toxicity." (PMID 35532120, 2022). "However, the relevance between CXCL12/CXCR4 and the differentiation of tumour cells towards Schwann‐like cell in PNI of SACC has not been investigated." (PMID 34170080, 2021). "In particular, BL-8040, a CXCR4 inhibitor, in combination with anti-PD-1 monoclonal antibody or chemotherapy has been shown to efficiently decrease MDSCs and increase CD8+ effector T cells in tumor tissues in patients with pancreatic cancer, resulting in better clinical outcomes." (PMID 34885241, 2021). "The G protein-coupled receptor chemokine (C-X-C motif) receptor 4 (CXCR4) is the membrane receptor for the chemokine CXCL12 and was originally identified in peripheral blood leukocytes and other cell types like hematopoietic stem cells, stromal fibroblasts and tumor cells." (PMID 34440844, 2021). "We hypothesized that the incongruence of the imaging data from these two modalities are a reflection of non-linear differential expression of CXCR4 between the vascular and tumor compartments within the same tumor model." (PMID 34793563, 2021). "Furthermore, TGFβ inhibitor significantly retarded tumour formation, while reducing cell migration and invasion abilities, tumour mass, and the number of metastatic foci derived from orthotopically implanted ALDH+ CD44+ CXCR4+ CD24+ subpopulation." (PMID 34247196, 2021). "Another study reported that blockade of CXCR4/CXCL12 signaling with Plerixafor could also alleviate the desmoplasia and immunosuppression, in turn decompressing tumor vessels and increasing T cell infiltration, eventually enhancing immunotherapy in cold breast tumors." (PMID 34138315, 2021). "Importantly, direct exposure of NLRP3 activating alum crystals or of the NLRP3 inhibitor as well as of blocking antibodies directed against CXCR2 or of the CXCR4 inhibitor did not significantly change the proliferation of SCC VII or 4T1 tumor cells in vitro." (PMID 34876407, 2021).